IL6 (interleukin 6)
Diseases named in the same sentence as IL6 in open-access papers (continued):
Sharing a sentence is not in itself a finding about the gene and the disease.
colorectal cancer (continued). "Tyciakova observed that TNF-α overexpression is accompanied by a significant upregulation of the proinflammatory cytokine IL-6 gene in A375 melanoma cells and proapoptotic ligand TRAIL gene in colorectal cancer cell HT29, both of which were mediated by TNF-α/TNFR1 signaling." (PMID 38656555, 2024). "A small matched cohort study on patients with intra-abdominal infection suggested that IL-6 and VEGF were increased up to at least four days after colorectal cancer surgery, and that patients with infection had a substantially higher risk of cancer recurrence than controls." (PMID 39167197, 2024). "Significant differences were observed between patients with gastric and colorectal cancer experiencing CAC, showing that increased IL-6 was found in patients with gastric cancer CAC and patients with colorectal cancer CAC exhibiting high IL-6, TNF-α, platelet, white blood cell count, FFA, and ApoA." (PMID 38730660, 2024). "Immunohistochemistry results indicated that THZ2 could prevent the up-regulation of the expression of COX-2, IL-6, β-catenin, and snail in AOM/DSS-induced colorectal cancer tissues." (PMID 38540292, 2024). "Actually, CAF-derived IL-6 and JAK/STAT3 pathway have been demonstrated to involve in treatment resistance in multiple other cancers, including pancreatic cancer, cholangiocarcinoma, colorectal cancer and breast cancer." (PMID 38311608, 2024). "In this study, we investigated the potential of preoperative inflammatory serum markers, including Interleukin-6 (IL-6), C-reactive protein (CRP) and Interleukin-8 (IL-8), as biomarkers for long-termn survival in patients with curatively resectable colorectal cancer (CRC) and liver metastases." (PMID 38233759, 2024). "IL-6 is an important pro-inflammatory protein significantly involved in the initiation, proliferation, epithelial-to-mesenchymal transition (EMT), invasiveness and metastasis of colorectal cancer cells." (PMID 39167197, 2024). "CRP, procalcitonin, TNF‐α, IL‐6, IL‐10, and WBC have been used as the most common markers of inflammatory stress, and Chen used these indices to compare the efficacy of laparoscopic surgery and conventional surgery in the treatment of colorectal cancer." (PMID 38351544, 2024). "In this study, we demonstrated that IL-6 activates the Src-FAK signaling cascade, leading to the recruitment of C/EBPβ, NFκB and STAT3 to the promoter region of Twist to increase Twist expression and induce EMT in HCT116 colorectal cancer cells." (PMID 37047623, 2023). "For example, Beclin1/autophagy signaling mediates Sox2-promoted chemoresistance, proliferation, stemness, migration, and invasion in colorectal cancer cells, and IL-6 activates autophagy via the IL-6/JAK2/BECN1 pathway, promoting chemotherapy resistance in colorectal cancer." (PMID 37303041, 2023). "In this study, it was shown that IL-1β, IL-6, and TNF-α are present from the early stages of colorectal cancer compared to the control group, and the levels could be used for diagnostic purposes." (PMID 38137862, 2023). "For instance, IL-6 in liver cancer and SPARC in colorectal cancer have been found to be affected." (PMID 37510502, 2023). "IL-6 is a main proinflammatory cytokine that activates signal transducer and activator of transcription 3 (STAT3), and has a key role in the pathogenesis of UC and the carcinogenesis of colorectal cancers related to UC." (PMID 38091316, 2023). "Macrophages cocultured with MTA1-overexpressing colorectal cancer cells significantly upregulated the M2-like macrophage markers Arg-1, CD206 and Ym1 but significantly downregulated the expression of the immunostimulator IL-6." (PMID 35350571, 2022). "Surprisingly, a preclinical study in ApcMin/+ colorectal cancer mice showed that treadmill running (1 h at 18 m/min speed and 5% grade, 6 days/week, 8 weeks) does not suppress systemic IL-6 overexpression induced by electroporating IL-6 plasmid in quadriceps." (PMID 35626116, 2022).
colorectal cancer (continued). "Furthermore, in this study, the same bacteria that correlated with IL-6, CRP, and TNF-α levels in the GI microbiota dysbiosis mice have been detected in fecal and tumor samples of patients with breast, cervical, and colorectal cancer." (PMID 35740687, 2022). "We aimed to analyze the levels of interleukin-6 (IL-6), tumor necrosis factor-α (TNF-α) and interleukin-12 (IL-12p70) in colorectal cancer and evaluate the predictive significance of clinical efficacy of patients with colorectal cancer treated with anti-vascular therapy combined with chemotherapy." (PMID 36226059, 2022). "The role of IL-6 and STAT3 in promoting colorectal cancer has previously been reported." (PMID 35205671, 2022). "miR-31 transcription activated in colorectal cancer cells in response to TNF-α and IL-6." (PMID 35967345, 2022). "In another study, IL-6 modulated the immune status of TME, increasing the antitumor effector function of CD8 + T cells and IL12 production by CD11c + dendritic cells, leading to increased metastatic colonization of colorectal cancer cells." (PMID 35626741, 2022). "The relationship between the levels and the clinical characteristics of patients was observed; the factors affecting the levels of IL-6, TNF-α, and IL-12p70 in colorectal cancer patients were analyzed, and the predictive validity of the efficacy of anti-vascular therapy was evaluated." (PMID 36226059, 2022). "Moreover, the increased levels of IL-6 and TNF-α following 5-FU-treated colorectal cancer cells have been reported." (PMID 35366874, 2022). "Colorectal carcinoma cell lines express IL-17R and are able to secrete VEGF and IL-6." (PMID 35626056, 2022). "Interestingly, the stimulation of colorectal carcinoma cells by IL-17 induces the production of angiogenic molecules such as VEGF and IL-6." (PMID 35626056, 2022). "In addition to PGE2, numerous inflammatory cytokines have also been shown to be involved in initiation, and progression of colorectal cancers, such as tumor necrosis factor α (TNF-α), and interleukin 6 (IL-6)." (PMID 34267186, 2021). "There is a correlation between tumor-derived IL-6 and macrophage MMP12 in colorectal cancer." (PMID 34863141, 2021). "A study investigating the impact of 5-FU chemotherapy on gut inflammation showed that in AOM/DSS-induced colorectal cancer model mouse treated with 5FU, significantly elevated expression of intestinal inflammatory genes was found, including TNF-α, MCP-1, NOS2, IL6, IL1-β, and FOXP3." (PMID 34337082, 2021). "IL-6 is also known to act via hypoxia-inducible factor (HIF)-1α to increase VEGF expression and this process has been shown to be inhibited by miR-451 mediated regulation of IL-6R expression in colorectal cancer cells." (PMID 32321512, 2020). "In colorectal cancer cells, β-catenin regulates the activity of the NF-κB promoter, whereas inhibition of GSK-3β by lithium or siRNA potentiated TNF-induced expression of IL-6 and CCL2 in human microvascular endothelial cells." (PMID 33171974, 2020). "In our study, it was IL-6 that showed a significant increase in each group with colorectal cancer, without any connection with the degree of differentiation." (PMID 32963755, 2020). "Furthermore, in colorectal cancer Mir34a was shown to constrain carcinogenesis by directly inhibiting an IL-6R/STAT3/Mir34a feedback loop, and its ablation is required to induce IL6-mediated EMT and invasion." (PMID 32541781, 2020). "Moreover, dietary cocoa ameliorates the inflammatory mediators, IL-6 and MCP-1, in diet-induced obese mice and inhibits colorectal cancer induced by AOM/DSS." (PMID 31489936, 2019). "Therefore, we examined 6 common cytokines (IL-1β, IL-2R, IL-6, IL-8 IL-10 and TNF-α) and found colorectal cancer derived HT29 and SW480 cells expressed IL-8 and further increased after irradiation." (PMID 31706322, 2019). "Subsequently, we determined the effect of colorectal cancer-derived MSC-CM on colorectal cancer cells in the presence and in the absence of IL-6 antibody." (PMID 29348540, 2018).
colorectal cancer (continued). "We observed that anti-IL-6 antibody markedly attenuated the migration induced by CC-MSC-CM, which demonstrated that IL-6 has a significant role in the promotion of metastasis in colorectal cancer." (PMID 29348540, 2018). "No published studies have examined the use of IL-6 as a therapeutic target in pancreatic, gastric, bile duct or colorectal cancer." (PMID 30038723, 2018). "Still in colorectal cancer, the expression of IL‐6 and STAT3 and the absence of miR‐34 (altogether constituting an EMT‐maintaining loop) are associated with nodal and distant metastases in a cohort of 425 patients." (PMID 28599100, 2017). "It has been shown in animal model that enhanced production of IL-6 may increase inflammation and tumorigenesis in cancer, and MSI promotes cell proliferation and cancer growth of colorectal carcinoma." (PMID 27285760, 2016). "Thus, the aim of this study was to systematically analyze the impact of IL-6 classic and trans-signaling on the expression of CEACAM5 and CEACAM6 in colorectal cancer cells." (PMID 26673628, 2015). "Therefore, the objective of the current investigation is to assess the prognostic significance of preoperative serum VEGF, IL-6, and CRP levels as indicators of outcome in patients with colorectal cancer." (PMID 20465852, 2010). "This implies that prevention of human colorectal cancer by oestrogens does not involve any direct effect on IL-6 expression." (PMID 18205904, 2008). "Colorectal cancer is characterized by a significant increase in key areas, including: (i) cancer growth markers, specifically PCNA; (ii) cancer metastasis biomarkers, such as MMP-9 level; (iii) inflammation markers, like IL-6; and (iv) DNA fragmentation as an apoptotic biomarker." (PMID 41307829, 2025). "Furthermore, the study suggests that the IL-6/STAT3 pathway enhances miR-92a expression by directly targeting its promoter, resulting in the activation of Wnt/β-catenin signaling and the subsequent promotion of stem-like traits in colorectal cancer cells." (PMID 38534736, 2024). "Notably, the interleukin-6 (IL-6) family of cytokines, including IL-6, IL-11 and leukaemia inhibitory factor (LIF), directly activate STAT3 and contribute to the establishment and progression of colorectal cancer." (PMID 38600086, 2024). "The data suggest that IL-6 produced by CAFs in the tumor microenvironment after D + Q treatment plays a critical role and may be responsible for the accelerated migration and EMT signature of MC38 colorectal cancer cells." (PMID 38612842, 2024). "Furthermore, IL-6 production is not restricted to patients with advanced disease as PBMCs from patients with primary colorectal cancers and radically resected stage III melanomas (MM 0) also showed enhanced production." (PMID 39518029, 2024). "IL-6 is a negative prognostic factor in many solid tumors, including colorectal cancer." (PMID 36851213, 2023). "A previous report showed that IL-6/STAT3 inflammatory signaling axis induces the deacetylation of FOSL1 at the Lys-116 residue located within its DNA binding domain, leading to the increase of FOSL1 transcriptional activity and acquisition of colorectal cancer (CRC) stem-like properties (stemness)." (PMID 37642779, 2023). "miR-34a participates in a feedback loop in which interleukin-6 (IL-6) mediates the repression of miR-34a, leading to the activation of IL-6R and STAT3, which in turns maintains the repression of miR-34a that helps to support a mesenchymal pro-metastatic phenotype in colorectal cancer cells." (PMID 35309939, 2022). "It worth to mention that a trial declared that combination of interleukin-6, piRNA, and a kind of micro RNA can lead to the transformation of cancer cells into CD4 + cells and therefore, it can be a useful procedure, in coming years, as combined therapy for colorectal cancer." (PMID 34193172, 2021).
colorectal cancer (continued). "Inhibition of HDAC activation or neutralization of IL-6 in colorectal cancer tissues can down-regulate the expression of immunosuppressant and chemotaxis-related genes in myeloid cells, confirming the importance of HDAC activation and IL-6 signaling pathways in the function and chemotaxis of MDSCs." (PMID 33027968, 2020). "Significant positive correlation between IL-6 and CRP serum levels was confirmed in the patients with CRC strongly suggesting that CRP as a general marker of inflammation should be combined with the other inflammatory molecules in patients with colorectal cancer." (PMID 30154846, 2018). "In contrast, the length of the colon in mice from the IL-6tm1Kopf-AOM-DSS group (5.48 ± 0.30 cm) was longer than in mice from the AOM-DSS control group, implicating that lack of IL-6 may delay tumorigenesis of colorectal cancer." (PMID 29707119, 2018). "However, previous research performed in non-orthopedic patients (i.e., cardiovascular and colorectal cancer) demonstrates that the NLR associates with other common indices of systemic inflammation, such as C-reactive protein and interleukin-6." (PMID 27848053, 2017). "In addition, our results indicate IL-6/STAT3 pathway increases miR-92a expression by directly targeting its promoter, resulting in Wnt/β-catenin signaling activation and consequent promotion of stem-like phenotypes of colorectal cancer cells." (PMID 29254202, 2017). "In addition, the Sphk1 inhibitor N′-(3-(benzyloxy) benzylidene)-3,4,5-trihydroxybenzohydrazide also decreased expression of interleukin IL-6 and cyclooxygenase-2 (COX-2) and significantly inhibited ulcerative colitis—a precancerous lesion of colorectal cancer—in a DSS-induced rodent model." (PMID 28991193, 2017). "To understand the impact of IL-6 on colon cells, we first analyzed by reverse transcription polymerase chain reaction (RT-PCR) whether mucosa-derived colon cell lines (CSC1, NCM460) and colorectal cancer cell lines (Caco-2, HT29p, HT29c, SW480) express key components of the IL-6 signaling pathway." (PMID 26673628, 2015). "Previously, we also reported that CRP levels reflect IL-6 production in colorectal cancer tissues and predict poor prognosis in colorectal cancer patients, particularly in stage I or II patients who are not usually candidates for postoperative adjuvant chemotherapy." (PMID 23833661, 2013). "Conversely, Actinomyces-induced interleukin-6 (IL-6) secretion may activate the JAK2/STAT3 pathway, increasing hepcidin production and systemic iron sequestration, a mechanism analogous to gut microbiota-mediated inflammatory pathways observed in colorectal cancer progression." (PMID 40149653, 2025). "Moreover, colorectal cancer cell growth and progression are promoted by CAF-derived IL-6; a vicious circle of colorectal cancer growth and progression is formed when IL-6 from CAFs induces STAT3 activation, which promotes the production of autocrine IL-6 in CAFs." (PMID 36635302, 2023). "In one study on colorectal cancer, PTX3 emerged as a significant prognostic factor; in comparison, other markers, such as IL-6 and TNF-α, did not demonstrate the same prognostic utility." (PMID 39594709, 2024). "Although data on IL6 mRNA levels are not shown due to undetectable expression in the SW620 cell line, PPARG and TGFB1 mRNA levels decreased after colorectal cancer tumorsphere generation." (PMID 39336151, 2024). "In addition, the expression of RIPK2 is positively correlated with IL-6, IL-8 and VEGF, which play a role in colorectal cancer, indicating that RIPK2 may be involved in the occurrence of colorectal cancer and that the expression level of RIPK2 is correlated with the prognosis of colorectal cancer." (PMID 35473583, 2022). "After 48 h of treatment with a cytokine mixture, TNF-, IL-1, and IL-6 relative mRNA increased in HT-29 and HCT-116 colorectal cancer cells, compared to the negative control." (PMID 36104433, 2022).
colorectal cancer (continued). "After ruling out TNFα, IL1β, IFNα and IFNγ, the authors show that IL6 induces the MSH3 nuclear-to-cytosol compartmental shift, and is coincident with the generation of oxidative stress within colorectal cancer cells and non-transformed colon cells." (PMID 25836926, 2015). "The therapies developed against these studied cytokines—IL-1β, IL-6, and TNF-α—can represent alternatives to current chemotherapeutic and immunological treatments, considering the toxicity and lack of effectiveness of chemotherapy in colorectal cancer." (PMID 38137862, 2023). "Furthermore, the present results showed that in DU-145 cells, IL-6 may be involved in activation of STAT-3 in an autocrine manner; IL-6 is higher in tumoral compared with non-tumorigenic tissue, in patients with breast and colorectal cancer and PCa." (PMID 35703345, 2022).